POSTN (periostin)
Diseases named in the same sentence as POSTN in open-access papers (continued):
Sharing a sentence is not in itself a finding about the gene and the disease.
liver fibrosis (14 papers, 2015 to 2025). "This study investigated the role and underlying mechanism of Periostin-expressing proliferative aHSCs the progression of liver fibrosis." (PMID 38216590, 2024). "Deficiency of Periostin led to reduced liver fibrosis and suppressed hepatocyte epithelial-mesenchymal transition (EMT)." (PMID 38216590, 2024). "To conclude, we show how liver fibrosis in preclinical models differentially correlates with TGFBi and POSTN levels in response to deficiency for Stab1 or Stab2, bearing consequences for potential anti-Stabilin therapies." (PMID 37446152, 2023). "POSTN was implicated in the development of liver fibrosis, whereas POSTN-deficient mice were protected from chronic liver damage in chronic CCl4 treatment as well as four weeks of MCD diet." (PMID 37446152, 2023). "It was previously reported that amelioration of liver fibrosis occurs in pro‐fibrotic models in POSTN‐deficient mice." (PMID 37357460, 2023). "Stab‐POSTN‐Triple deficient mice were generated to assess kidney and liver fibrosis and function in young and aged mice." (PMID 37357460, 2023). "In this study, we found that miR-876 and POSTN are also associated with liver fibrosis, and overexpression of POSTN increased the expression of collagen and α-SMA." (PMID 33083453, 2020). "Bmp-1 assumes a crucial function in this process by activating EGFR signalling in hepatocytes.Additionally, in fibrotic mice with a deficiency in Periostin, the reduction in liver fibrosis was counteracted by the introduction of exogenous Bmp-1, which coincided with the progression of EMT." (PMID 38216590, 2024). "Interestingly, upon the deletion of proliferative HSCs, the expression of Periostin was found to be reduced in the livers of αSMA-TK liver fibrosis mice, further supporting the significant association between Periostin and proliferative aHSCs." (PMID 38216590, 2024). "Considering the role of Periostin in the tissue microenvironment due to its secretory properties, it is intriguing to explore the cellular communication associated with Periostin in the context of liver fibrosis." (PMID 38216590, 2024). "The results of one article indicate the usefulness of the FIB-4 index, shear wave elastography, and serum periostin levels in diagnosing liver fibrosis among women with PCOS." (PMID 40283027, 2025). "The data suggest that dabrafenib has the potential to reverse liver fibrosis by inhibiting Periostin." (PMID 38216590, 2024). "In this study, we unveil a significant increase in proliferative aHSCs characterized by Periostin during liver fibrosis, highlighting their prominent role in the liver fibrogenesis." (PMID 38216590, 2024). "This study investigated the roles and mechanisms of Periostin in phenotypic transition of HSCs and relevant abnormal cellular crosstalk during liver fibrosis." (PMID 38216590, 2024). "Mechanistically, bone morphogenetic protein-1 (Bmp-1) is essential involved in the pro-fibrotic communication between Periostin-expressing aHSCs and hepatocytes, consequently promoting the progression of liver fibrosis." (PMID 38216590, 2024). "The findings provide evidence of the essential role of Bmp-1 in Periostin-provoked liver fibrosis through hepatocyte EMT." (PMID 38216590, 2024). "A potential synergistic effect of TNFα and IL-17 in periostin-mediated collagen deposition has been described in liver fibrosis." (PMID 35056404, 2022). "Periostin increased hepatic fibrosis and hepatic steatosis by inhibiting peroxisome proliferator-activated receptor-α(PPAR-α) expression." (PMID 36611844, 2022). "In chronic inflammation, such as in liver fibrosis, pro-inflammatory cytokines including TNFα and IL-17 are elevated and continue to drive periostin production, and thus, fibrosis of the liver." (PMID 35056404, 2022). "Periostin tempted liver fibrosis by activating LOX and lysyl oxidase-like (LOXL) in chronic liver disease via the αvβ3/PI3K/Smad2/3 signaling pathway." (PMID 36611844, 2022).
liver fibrosis (continued). "For instance, in collaboration with TNF-α, IL-17 promotes HepG2 cells to produce more periostin, which induces fibroblasts to synthesize additional type I collagen and aggravate liver fibrosis." (PMID 33869241, 2021). "Upregulation of periostin at both RNA and protein level was found in liver tissue of mouse models of liver fibrosis induced using CCl4 or BDL." (PMID 33262757, 2020). "miR-876 and POSTN were inversely correlated in HCC samples and associated with EMT status and liver fibrosis in clinical HCC tissues." (PMID 33083453, 2020). "In this experimental approach, periostin expression at liver tissue level and serum level was upregulated in mouse models of acute and chronic hepatic fibrosis, while this effect was abolished in the recovered livers after stopping CCl4 administration." (PMID 33262757, 2020). "In this study, our results showed the anti-fibrogenic effects of siRNA-periostin on hepatic fibrosis." (PMID 26249143, 2015). "To verify the expression of periostin in hepatic fibrosis, we determined the protein and mRNA levels of periostin in hepatic fibrosis tissues and HSCs." (PMID 26249143, 2015). "We found that siRNA-periostin attenuated liver fibrosis by inhibiting the transforming growth factor (TGF)-β1/Smad signalling pathway." (PMID 26249143, 2015). "We used RT-PCR and Western blot to evaluate the expression level of periostin in hepatic fibrosis tissues and HSCs, respectively." (PMID 26249143, 2015). "The periostin mRNA and protein expression in hepatic fibrosis tissues was increased significantly compared to that of controls (P < 0.05)." (PMID 26249143, 2015). "In line with the exacerbated liver fibrosis and elevated Bmp-1 levels, the expression of hepatocyte EMT markers, including N-cad, Vim, and EGFR was increased, while E-cad expression decreased in the livers of Periostin-deficient mice." (PMID 38216590, 2024). "Furthermore, liver fibrosis was alleviated in DDC-induced Periostin KO mice after administering rBmp-1." (PMID 38216590, 2024). "Overall, these findings suggest that Periostin may serve as a dependable marker for proliferative aHSCs during liver fibrosis." (PMID 38216590, 2024). "Importantly, elevated levels of Periostin were detected in the serum of patients with liver fibrosis, indicating a strong correlation between Periostin and the progression of liver fibrosis." (PMID 38216590, 2024). "Bmp-1 and Periostin should be potential therapeutic targets for liver fibrosis." (PMID 38216590, 2024). "We then investigated the role of Periostin in liver fibrosis using WT and Periostin KO mice." (PMID 38216590, 2024). "Stabilin ligand POSTN only correlated with the degree of liver fibrosis in WT and Stab1−/− mice across all experiments, while TGFBi, as a structurally similar ligand of both Stabilins, showed a very strong correlation with the degree of fibrosis in all genotypes in liver tissue." (PMID 37446152, 2023). "In this study, the role of periostin in liver fibrosis was investigated." (PMID 26249143, 2015). "Similarly, we found that the protein and mRNA expressions of periostin were higher in HSCs than in the quiescent cells, indicating that aberrant periostin expression is a general feature of hepatic fibrosis." (PMID 26249143, 2015). "In this study, the obvious up-regulation of periostin was observed in cirrhotic liver tissues and activated HSCs, which suggested that periostin may serve as a potential biomarker for hepatic fibrosis." (PMID 26249143, 2015). "However, studies focusing on the role of Periostin in liver fibrosis remain limited." (PMID 38216590, 2024). "Since these proteins showed strong effects on T cells in other inflammatory diseases, and on macrophage infiltration in hepatic fibrosis, a deeper understanding of periostin and EDP involvement in regulating these immune cells in NAFLD livers could provide new insights on disease progression." (PMID 33262757, 2020).
liver fibrosis (continued). "However, little is known about the role of periostin in hepatic fibrosis." (PMID 26249143, 2015). "In contrast, Stab‐1/2‐DKO mice present with liver fibrosis and glomerulofibrosis with increased abundance of TGFBI and POSTN, which is aggravated upon aging." (PMID 37357460, 2023). "By utilizing Periostin KO mice, we demonstrated that the absence of Periostin markedly reduced liver fibrosis." (PMID 38216590, 2024). "Periostin-overexpressing HSCs, exhibiting a proliferative aHSC phenotype, release bone morphogenetic protein-1 (Bmp-1), which activates EGFR signaling, inducing hepatocyte EMT and contributing to liver fibrosis." (PMID 38216590, 2024). "As we did not observe alterations of liver fibrosis in Stab‐POSTN‐TrKO mice compared to Stab1/2‐DKO mice, this indicates alternative mechanisms of liver fibrosis that are independent of POSTN in Stab1/2‐DKO mice." (PMID 37357460, 2023). "The median plasma periostin concentration was 11.6 ng/mL without differences amongst groups; it was not influenced by age, liver fibrosis or steatosis." (PMID 33255560, 2020). "For POSTN, WT mice showed a very high correlation with liver fibrosis (R2 = 0.58, r = 0.76, p < 0.0001), while Stab1−/− showed a moderate to high correlation (R2 = 0.24, r = 0.49, p = 0.0162) and in Stab2−/−, POSTN levels did not correlate with liver fibrosis levels (p = 0.2193)." (PMID 37446152, 2023). "In conclusion, these results suggest that periostin may function as a novel regulator to modulate HSC activation, potentially by promoting the TGF-β1/Smad signalling pathway, and propose a strategy to target periostin for the treatment of liver fibrosis." (PMID 26249143, 2015). "Stabilin‐1 and Stabilin‐2 scavenge their ligands POSTN and TGFBI from the circulation, no liver fibrosis and glomerulofibrosis is obvious in wildtype mice aged for 12 months." (PMID 37357460, 2023).
Obesity (14 papers, 2015 to 2025). Accumulation of substantial excess body fat. "It has also been reported that γδT cells secreted IL-17A, obesity induced GM-CSF and IL-5, periostin and Elf5 are associated with neutrophils recruitment in the lung." (PMID 33178575, 2020). "The abnormal expression of periostin in the liver is reported to be closely associated with glucose and lipid metabolic disorders and obesity in an obese mouse model." (PMID 27313402, 2016). "Interestingly, increased circulating periostin was described as a biomarker of increased risk to develop nonalcoholic fatty liver disease and insulin resistance during obesity." (PMID 30088333, 2018). "A significant inverse correlation between human periostin mRNA levels and obesity was observed in subcutaneous WAT (sWAT) as well as in visceral WAT (vWAT)." (PMID 30088333, 2018). "Recent study showed periostin play a pivotal role in abnormal liver triglyceride (TG) accumulation and in the development of obesity-related liver fat accumulation." (PMID 27885258, 2016). "Second, clinical heterogeneity (e.g., differences in the types of allergens, concomitant obesity) may have influenced periostin levels in this subgroup." (PMID 40981017, 2025). "Additionally, factors including smoking and obesity, prevalent in our cohort and known to modulate periostin levels inversely, potentially attenuate these associations." (PMID 41374409, 2025). "Nevertheless, it remains to be determined whether corticosteroids and obesity exert synergistic effects on periostin-induced PPARα downregulation and alteration in lipid metabolism in the liver." (PMID 35162986, 2022). "In addition, as obesity develops, the macrophages in visceral adipose tissue were demonstrated to secrete periostin, possibly in response to hypoxia." (PMID 32517742, 2020). "In this study, we hypothesized that a high level of serum periostin despite being overweight/obese may discriminate severe OSA or OSA with comorbidities from mild OSA with obesity alone." (PMID 32517742, 2020). "An elevated level of POSTN is important for the improvement of obesity and NIDDM, but this gene may be involved in insulin resistance." (PMID 30678306, 2019). "Periostin may act as a scaffold and remodeling protein in inflammatory responses, obesity, and insulin resistance, which may provide new molecular clues for the pathogenesis of T2DM and obesity." (PMID 27313402, 2016). "Periostin could mediates obesity-induced hepatosteatosis by promotes hepatic triglyceride accumulation by downregulation of PPARa9." (PMID 27885258, 2016). "In our study, we found that patients with obesity had significantly higher levels of periostin." (PMID 27313402, 2016). "There was a progressive increase in periostin expression from the NGT to the T2DM group, indicating that periostin was strongly correlated with obesity and T2DM, but the respective effects of obesity and T2DM on the expression levels of periostin remained unclear." (PMID 27313402, 2016). "Therefore, we speculate that obesity may involve this positive regulatory effect, and further studies are needed to clarify internal connections among periostin, HOMA-IR, and inflammation." (PMID 27313402, 2016). "In addition to insulin resistance and increased flux of NEFAs to the liver, indirect evidence also suggests that corticosteroids and obesity might favor hepatic steatosis via enhanced circulating levels of periostin, an extracellular matrix protein expressed in most tissues, including WAT and liver." (PMID 35162986, 2022). "In this study, we found that Chinese patients with obesity and T2DM have significantly higher plasma periostin levels than healthy subjects and that periostin is strongly associated with TG metabolism, chronic inflammation, and insulin resistance." (PMID 27313402, 2016).
Obesity (continued). "Bone turnover markers, sclerostin, periostin and semaphorin 4D were assessed before and 1, 12 and 24 months after SG, and aBMD was determined by DXA at baseline and after 12 and 24 months in 83 patients with obesity." (PMID 37892386, 2023). "In a cross-sectional study in young women, periostin was lower in OB compared to NW controls and women with anorexia nervosa; however, there are no published data on how periostin relates to bone strength in obesity." (PMID 36173650, 2022). "Therefore, we hypothesized that high serum periostin levels in patients with OSA, despite being overweight/obese, may discriminate severe OSA or OSA with comorbidities from mild OSA with obesity alone." (PMID 32517742, 2020).
osteoarthritis (14 papers, 2015 to 2025). A noninflammatory degenerative joint disease occurring chiefly in older persons, characterized by degeneration of the articular cartilage, hypertrophy of bone at the margins and changes in the synovial membrane. "In the joints, POSTN promotes the expression of inflammatory cytokines and MMPs in chondrocytes and synoviocytes, causing apoptosis, which leads to osteoarthritis." (PMID 38020106, 2023). "Elevated levels of periostin (Postn) in the cartilage and bone are associated with osteoarthritis (OA)." (PMID 33832532, 2021). "Moreover, POSTN deficiency prevents age-related spontaneous osteoarthritis, suggesting a link between POSTN and aging in the cartilage." (PMID 38020106, 2023). "Based on the synovial fluid analysis, POSTN was more highly expressed in subacute anterior cruciate ligament (ACL) injury than in osteoarthritis." (PMID 38020106, 2023). "POSTN expression-mediated musculoskeletal diseases associated with SASP include osteoporosis, osteoarthritis, IVDD, and LSS." (PMID 38020106, 2023). "POSTN expression is elevated in osteoarthritis cartilage and also significantly increased in the cartilage of surgically-induced osteoarthritis rats." (PMID 38020106, 2023). "Periostin is used as biomarker for multiple diseases, and it is part of the pathogenesis of periodontitis and osteoarthritis." (PMID 38962283, 2024). "Furthermore, POSTN expression was elevated in the synovial fluid of patients with osteoarthritis with the progression of osteoarthritis grade, suggesting that it is associated with osteoarthritis." (PMID 38020106, 2023). "Additionally, gene expression analysis of osteoarthritis cartilage is underway, and a link to POSTN in cartilage metabolism has been highlighted." (PMID 38020106, 2023). "Emerging knowledge has highlighted the role of periostin (POSTN) in osteoarthritis (OA) process; however, whether POSTN is suitable as a biomarker of OA remains unclear." (PMID 36451121, 2022). "Moreover, many other studies have elucidated the role and mechanism of POSTN in osteoarthritis." (PMID 38020106, 2023). "Thus, POSTN is also expected to be applied to cartilage regeneration therapy, which may lead to multifaceted osteoarthritis treatment." (PMID 38020106, 2023). "Notably, several other hub genes and genes associated with upstream regulators highlighted in our study—such as TIMP2, POSTN, and CHI3L1—are also critical regulators of ECM remodeling in other degenerative and fibrotic conditions, including osteoarthritis." (PMID 40565255, 2025). "Furthermore, in osteoarthritis synovial cells, IL-13 activated signal transducer and activator of transcription 6 (STAT6) to upregulate POSTN expression." (PMID 38020106, 2023). "POSTN-mediated chondrocyte apoptosis and ECM degradation have been reported to promote cartilage degeneration and osteoarthritis; therefore, it can be inferred that a similar mechanism may be responsible for osteoarthritis changes in the cartilage component of the IVD." (PMID 38020106, 2023). "Serum periostin levels do not need to be adjusted to take account of a patient’s age, sex, or common comorbidities, although periostin levels may be lower in smokers, in those with elevated BMI, and those with pre-extant osteoarthritis, and may be raised in a number of cancers." (PMID 30065761, 2018). "Higher levels of monomeric periostin in RA patients without ILD may be explained by previous studies in which the expression of periostin was increased in serum, synovium tissue, and synovial fluid of RA patients compared with healthy controls or osteoarthritis patients." (PMID 38002712, 2023).